KRTAP2-4 (keratin associated protein 2-4)
Description:
In the hair cortex, hair keratin intermediate filaments are embedded in an interfilamentous matrix, consisting of hair keratin-associated proteins (KRTAP), which are essential for the formation of a rigid and resistant hair shaft through their extensive disulfide bond cross-linking with abundant cysteine residues of hair keratins. The matrix proteins include the high-sulfur and high-glycine-tyrosine keratins (By similarity).
Synonyms: KAP2.4; KRTAP2.4; KAP2.1B
Tractability: No criterion of Open Targets' tractability assessment is met for any kind of drug.
Gene: Protein-coding gene on chromosome 17 (41,065,116 to 41,065,879, reverse strand). Ensembl gene ENSG00000213417.
Pathways (Reactome):
Developmental Biology: Keratinization
Gene Ontology:
Molecular function: protein binding
Cellular component: cytosol; keratin filament
Genetic constraint (gnomAD): Loss-of-function variants: 6 observed, 8.07 expected, observed/expected ratio (o/e) 0.74, 90% interval 0.41 to 1.45. That is too few expected variants to judge how well the gene tolerates losing a copy. Missense variants: 86 observed, 136.48 expected, observed/expected ratio (o/e) 0.63, 90% interval 0.53 to 0.75. Synonymous variants: 47 observed, 52.82 expected, observed/expected ratio (o/e) 0.89, 90% interval 0.7 to 1.13.
Homologues: Orthologues: mouse Krtap5-24 (43% identical), mouse Krtap5-26 (38% identical), mouse Krtap5-2 (36% identical), rat Krtap5-8 (35% identical), rat AABR07006049.1 (34% identical), mouse Krtap5-20 (33% identical). Paralogues in human: KRTAP2-3 (100% identical), KRTAP2-1 (99% identical), KRTAP2-2 (95% identical), KRTAP4-12 (52% identical), KRTAP4-6 (52% identical), KRTAP4-3 (51% identical), KRTAP4-11 (50% identical), KRTAP4-5 (50% identical), KRTAP4-9 (48% identical), KRTAP4-4 (46% identical), KRTAP9-1 (46% identical), KRTAP10-11 (45% identical), and 35 more.